IL1B (interleukin 1 beta)
Diseases named in the same sentence as IL1B in open-access papers (continued):
Sharing a sentence is not in itself a finding about the gene and the disease.
tumor (continued). "However, the precise mechanisms of IL-1β production and maturation in the tumor microenvironment are largely unknown." (PMID 30586442, 2018). "Therefore, blockade of IL-1β may constitute an important therapeutic rationale to impair tumor development and progression." (PMID 30042333, 2018). "However, conflicting effects of IL-1β in terms of tumor development have been observed." (PMID 30042333, 2018). "In addition to playing a role in tumour growth, IL-1B has been reported to control tumour invasion." (PMID 29760166, 2018). "Besides, tumor neoangiogenesis was shown to be promoted by IL-1β induced COX-2." (PMID 29983861, 2018). "In addition, in the case of chronic inflammation, sustained IL-1β may promote both tumor induction and later on also tumor propagation by different mechanisms." (PMID 30042333, 2018). "The inflammasome/IL-1β pathway in the tumor microenvironment may be involved in IRAK1 effects." (PMID 30279971, 2018). "Compounds that block IL-1β-mediated pathways could potentially attenuate tumor progression." (PMID 29364159, 2018). "However, systemic IL-1β inhibition may compromise anti-tumor immune responses that depend on immunogenic cell death, and immune responses against infections." (PMID 29983861, 2018). "Likewise, the roles of IL-1β in the tumor microenvironment are controversial." (PMID 30586442, 2018). "However, IL-1β generated in the course of chronic inflammation supports tumor development." (PMID 30042333, 2018). "IL-1B and IL-1A may both play roles in tumour formation and progression to metastasis." (PMID 29760166, 2018). "Importantly, tumors generated with 4T07 and 4T1 cells, but not 67NR cells, induced central pro-inflammatory cytokine production in both the hippocampus and cortex; specifically, there was a significant increase in the concentration of IL-1β for both 4T07 and 4T1 tumor bearing mice." (PMID 28811490, 2017). "Additionally, the expression level of IL-1β and IL-18 were reduced in tumor lesions." (PMID 28360909, 2017). "Real-time RT PCR assay showed that the levels of TNF-α and IL-1β, pro-inflammatory cytokines known as important factors for tumorigenesis, were elevated in extra- and intraorbital lacrimal glands receiving A20 cells, reflecting an inflammatory milieu in tumor-bearing glands." (PMID 29029511, 2017). "The fact that these three cytokines (IL-6, IL-1β, LCN2) were up-regulated in LuM cells indicates that these highly metastatic cells obtained through in vivo selection will be a useful resource for further studies on elucidating the mechanisms underlying cytokine-related tumor growth and metastasis." (PMID 28410227, 2017). "In an inflammatory tumor microenvironment, macrophages can be primed and activated by a variety of damage-associated molecular patterns (DAMPs) such as ATP, HMGB1, and BD-2, which are produced by apoptotic and/or necrotic cells to foster, among others, IL-1β production." (PMID 28804221, 2017). "Additionally, IL-1β blockade significantly decreased tumor development in another AOM/DSS mouse model, which might explain the less dysplastic lesions found in Cysltr1−/− polyps." (PMID 28410235, 2017). "Thus, IL-1β effect seems to be unidirectional from IRISOE tumor cells to MSCs." (PMID 29262555, 2017). "In addition, our western blot results showed that NLRP3, Caspase-1, IL-18 and IL-1β were highly expressed in the Tgfbr1/Pten 2cKO mice SCCHN tumor lysates compared with control wild type tongues, and the expression of BMI1, ALDH1 and CD44 were consistent with NLRP3 inflammasome." (PMID 28865486, 2017). "Moreover, alcohol increased IL-1β in control and tumor mice." (PMID 29245988, 2017). "However, our findings suggest that the stimulation of over-expressed P2X7R on HNSCC or epithelial cells produces active IL-1β via the NLRP3 inflammasome pathway independent of the surrounding tumor-associated macrophages." (PMID 28430665, 2017). "Moreover, IL-1β is a pro-inflammatory cytokine that promotes tumor invasiveness and metastasis." (PMID 28410227, 2017).
tumor (continued). "This study aimed to investigate whether IL-1β can differentially modulate in vitro tumour cell adhesion and transmigration to, and across, blood and lymphatic endothelium and to assess its ability to alter tumour cell migration." (PMID 28551814, 2017). "Mice with either 4T07 or 4T1 tumors had increased liver mRNA production of IL-1β (H = 34.10, p < 0.001), IL-6 (H = 29.12, p < 0.001), and TNFα (H = 35.31, p < 0.001) compared to either the vehicle or 67NR tumor-bearing mice (p < 0.05 in all cases, Dunn’s multiple comparisons)." (PMID 28811490, 2017). "Similarly, the increase in IL-1β production by PSP in the tumor microenvironment may have counterproductive effects on tumor growth since expression of IL-1β in the tumor milieu promotes tumor invasiveness, angiogenesis, and tumorigenesis." (PMID 28932226, 2017). "Likewise, PSP-induced increase of IL-6 expression, in the context of enhanced IL-1β and GM-CSF expression, may lead to increased levels of MDSCs or Tregs at the tumor microenvironment." (PMID 28932226, 2017). "IL-1β can facilitate tumor-associated inflammation, rendering the tumor stroma carcinogenic via the release of trophic factors such as FGF2 and VEGF which allow malignant cells, cancer-associated fibroblasts (CAFs) and endothelial cells to fuel and foster tumor cell survival and invasiveness." (PMID 27528423, 2016). "The close functional association between P2X7R and NLRP3 and the known, albeit controversial, role of IL-1β in tumor progression, initially prompted us to hypothesize that NLRP3 followed in CLL lymphocytes an expression pattern similar to P2X7R, and thus was overexpressed." (PMID 27221966, 2016). "Furthermore, TNF-α and IL-1β are important for the tumor suppressive effects of S. enterica." (PMID 27835896, 2016). "In short, this sequence of events causes the release of pro-inflammatory cytokines (IL-1β, IL-17, IFN-γ), promoting the activation, proliferation, and/or infiltration of cytotoxic T lymphocytes, γδ T cells and other immune cells that collectively mediate the destruction of tumor cells." (PMID 27854240, 2016). "IL-1β and TNF-α may alter stromal cells enhancing the expression of CCL2, CXCL8, and CCL5 by cancer-associated fibroblast and mesenchymal stem cells in the inflammatory tumor microenvironment of breast cancer." (PMID 27886105, 2016). "Thus, the neutralization of IL-1β reduced tumor growth and the tumor-induced angiogenesis." (PMID 26919112, 2016). "Activated macrophages have the capacity to secrete pro-inflammatory IL-1 cytokines, and since inflammation is crucial for gp130757FF tumor development we assessed whether activated macrophages contribute to elevated IL-1α and IL-1β expression in 30 week old gp130757FF mice." (PMID 25528766, 2015). "In contrast, rejection is associated with massive infiltration of the tumor bed by leukocytes, predominantly ED1+ microglia/macrophages, CD4+ T helper cells and CD8+ effector cells, and correlates with elevated serum levels of pro-inflammatory cytokines IL-1β, IL-18 and TNF-α." (PMID 26291724, 2015). "Next we examined whether IL1β can promote tumor growth in our murine Proneural GBM model." (PMID 25987130, 2015). "Tumor formed by K562 cells transfected for a new mutation (A559-to-G substitution) showed a proliferative advantage and higher expression of VEGF and MCP1, and haplotypes of the P2X7R containing the rs1718119 polymorphism have been linked to an enhanced IL-1β secretion." (PMID 26337470, 2015). "Thus, according to our findings, a broad spectrum of pathogens or molecules recognized by the PRRs could induce the EGFR signaling cascade through trigger IL-1β production, and such that the cascade exerts its tumor-promoting role." (PMID 26462152, 2015). "Thus, IL-1β provides the inflammatory microenvironment for angiogenesis and tumor progression." (PMID 24734023, 2014).
tumor (continued). "Gelatinase B/MMP-9 activates pro-inflammatory cytokines TNFα and IL-1β, increases the activity of chemokines CXCL1, CXCL4, CXCL7 and CXCL8, releases TGFβ from matrix stores, is released by activated neutrophils in TIMP-1-free form and acts as a nanomolar effector of tumour associated inflammation." (PMID 24473089, 2014). "We have hypothesized that initially small amounts of tumor cell-derived IL-1β induce a local inflammatory response, which subsequently recruits and activates BMDs that further secrete IL-1β, as well as an entire cytokine network that promotes tumor-mediated angiogenesis and tumor progression." (PMID 24734023, 2014). "It is also noteworthy that, unlike IL-1β, the elevated levels of IL-1α in normal skin keratinocytes was sufficiently high in this assay to mask any quantifiable effect of IL-15 on IL-1α protein expression within the underlying tumor." (PMID 24416335, 2014). "TNF-α and IL-1β are the most potent pro-inflammatory cytokines produced by TAMs which, depending on their concentration, may either induce the expression of several genes resulting in the promotion of tumor cell aggression, or exert a cytotoxic effect." (PMID 25120672, 2014). "Thus, in the tumor microenvironment, carcinoma-derived IL-1 (IL-1α and IL-1β) activates mesenchymal stem cells (MSCs) to produce PGE2 and other cytokines, such as IL-6, IL-8, Gro-α, and RANTES that in turn act on the carcinoma cells and induce activation of β-catenin and transition into CSCs." (PMID 23847618, 2013). "Therefore there might be a very different effect of inflammasome activity outside of the gut, wherein secreted IL-1β and IL-18 actually suppress tumor surveillance by innate cells but perhaps ultimately promote adaptive immunity to tumor antigens." (PMID 24409181, 2013). "Thus, in mice deficient in IL-1β, almost no inflammatory response was observed during tumor development, lack of IL-1α did not impair inflammation as compared to WT mice, while an heightened inflammatory response was evident in IL-1Ra KO mice." (PMID 23847618, 2013). "Furthermore, the results of our IHC analysis also indicate that primary tumours from patients who eventually developed brain metastasis (n = 6) expressed significantly higher IL-1β compared to the tumours from overall metastasis-free patients with the similar clinical grades (n = 11)." (PMID 23495140, 2013). "Thus, this study has characterized IL-1β as a major mediator in the tumor microenvironment that recruits MDSCs and also controls their immature pro-invasive and immunosuppressive state; ablation of IL-1β alters the pro-tumor microenvironment into an anti-tumor one." (PMID 23847618, 2013). "Furthermore, they found that HMGB1 from dying tumor cells is critical for IL-1β release by DCs." (PMID 24409181, 2013). "Furthermore, examination of the oro-pharyngeal tumour samples at an mRNA level revealed that if IL1B is elevated in the stroma of the tumour compared to the stroma of matched non tumour tissue, patients have a more favourable outcome, than those where IL1B levels were reduced in the tumour samples." (PMID 23867201, 2013). "Thus, secreted IL-1β serves as both an initiator and a tumor promoter." (PMID 23847618, 2013). "We hypothesize that IL-1α in the tumor microenvironment is immunostimulatory, rather that inflammatory, due to its localization on the surface of cells and its limited secretion, as compared to IL-1β." (PMID 23847618, 2013). "The production of chemokines and cytokines such as TNF-α, IL-6, and IL-1β by activated macrophages plays a critical role in diverse physiological processes, particularly in a host's innate immunity system to inhibit microbial growth, tumor cell growth, and tumor metastasis." (PMID 24574581, 2013).
tumor (continued). "In addition to understanding the diverse functions of IL-1β in the interaction between tumor cells and immune response, the production of IL-1β from tumor cells induced by growth factor is a crucial issue for the development of novel therapeutic modalities based on intervention in IL-1β expression." (PMID 23383347, 2013). "However, following tumor progression, high level of IL-1β, and possibly IL-23 as well, with the reduced levels of IL-6 and TGF-β may become supporting cytokine milieu for the expansion of Th17 cells in tumor tissues." (PMID 22994684, 2012). "Thus, anti- IL-1β therapy may act on several levels; reduce tumor cell adhesion, maintain peritoneal integrity, and ameliorate peritoneal tumor cell induced inflammatory responses that may exacerbate adhesion and establishment of secondary tumors." (PMID 22296757, 2012). "In addition, tumour-derived IL-1β may potentially induce dendritic cell-dependent adaptive immunity against tumours." (PMID 23065753, 2012). "Thus far, the exact mechanisms by which IL-1β promotes tumor growth have remained unclear." (PMID 23174018, 2012). "In addition to its role in angiogenesis, we hypothesized that IL-1β contributes to the progression of RCC by directly affecting tumor cell invasion." (PMID 23342250, 2012). "Thus, our results suggest that therapeutic treatment can cooperate with PAMPs and DAMPs in a tumour microenvironment to induce more IL-1β secretion, which consequently results in efficient tumour suppression by recruiting neutrophils, especially immunostimulatory N1 TANs." (PMID 23065753, 2012). "In addition to their ability to promote the release of CCL2 and CCL5 by the tumor cells, it is possible that TNFα and IL-1β act directly to elevate processes that are required for local recurrence or metastasis formation, which identify the IDC-with-relapse group of patients." (PMID 21486440, 2011). "We showed that macrophages and IL-1β stabilized Snail in tumor cells in an NF-κB/Wnt dependent manner and that Snail deficient tumor cells were not protected from TRAIL-induced apoptosis by macrophages or by IL-1β, demonstrating a crucial role of Snail in the resistance of tumor cells to TRAIL." (PMID 20661477, 2010). "Cytokines secreted by the activated tumor stroma modulate tumor growth and regulate their survival and invasiveness through activation of oncogenic signaling pathways in tumor cells, examples being activation of NF-κB by TNFα and IL-1β, and activation of STAT3 by IL-6." (PMID 20661477, 2010). "Furthermore, serum levels of IL-1β and IL-6 correlate with tumor response to anti-VEGF therapy and may be predictive clinical markers." (PMID 19888452, 2009). "Moreover, owing to its pro-inflammatory nature, IL-1β is regarded a tumor-promoting cytokine." (PMID 18801189, 2008). "The fact that endothelial cells undergoing apoptosis release interleukin -1 β (IL-1β) that via a paracrine loop in turn stimulates the expression of adhesion molecules on the endothelial cells suggests that the following sequence of events for the recurrence of tumour cells at distant sites occur." (PMID 17088916, 2006). "IL-37 suppresses many pro-inflammatory pathways, including NF-κB, MAPK, and the cytokines IL-1β, IL-6, and TNF, thereby inhibiting tumor growth." (PMID 41596472, 2026). "scRNA-seq revealed cell-type-specific expression patterns, where IL1B was significantly upregulated in both tumor epithelial and myeloid cells, and IL10 was specifically elevated in tumor epithelial cells." (PMID 41983192, 2026). "Coordinated signaling between IL-1β and CXCL8/IL-8 promotes neutrophil recruitment, stimulates tumor-angiogenesis, and provokes EMT programs at invasive tumor margins, which facilitate inflammatory microenvironments that drive tumor progression." (PMID 41596524, 2026).
tumor (continued). "Kaempferol, a major flavonol widely found in various fruits and vegetables, downregulated the expression of key inflammatory mediators (IL-1β, CXCL8, and MMP9), then reducing neutrophil infiltration and activation while inhibiting tumor growth in CRC." (PMID 41601690, 2026). "In 4T1 tumor‐bearing mice, PCN significantly elevated serum levels of IL‐6, IL‐12, and IL‐1β, comparable to LPS‐induced fever, while promoting dendritic cell maturation and robust CD8+ T cell infiltration." (PMID 41298282, 2026). "In response to interleukin-1β (IL-1β) stimulation, PCAF translocated to mitochondria in cancer cells and protected tumor cells from iron metamorphosis." (PMID 40664718, 2025). "Using next‐generation sequencing, we found that in tumor tissues with high CCL24 expression, iCAF markers (IL1A, IL1B, IL6, CXCL1, and CXCL5) were significantly highly expressed, indicating high infiltration of iCAFs in the TME." (PMID 40397411, 2025). "This is also accompanied by a reduction in tumor infiltration by CD8+ resident memory cells, Tregs, IL1B+ monocytes, and CCL2+ fibroblasts." (PMID 40027748, 2025). "Particularly, IL-1β, the β subunit of IL-1, has been demonstrated to significantly alter the TME and subverting anti-tumor immunity beyond directly promoting tumor cell proliferation." (PMID 39948655, 2025). "Moreover, elevated IL-1β levels observed in various GBM cell lines, including CCF3 and U-87, U373MG and in human GBM tumor samples were associated with the activation of the NF-κB and mitogen-activated protein (MAPK) signaling cascades, enhancing tumor cell invasiveness." (PMID 40497976, 2025). "In preclinical studies, combinations of therapies such as anti-IL-1β and cabozantinib have been shown to enhance CD4 + effector T cell responses and increase naive T cells in tumor-draining lymph nodes." (PMID 41035074, 2025). "In an orthotopic CRC mouse model, CTCF-over-expressing TANs increased tumor growth and TAN infiltration, which was attenuated by MIEN1 knockdown or IL-1β neutralization." (PMID 40959269, 2025). "Downstream analysis of genes involved in the migration of tumor cell lines revealed that MSI2 was the top regulator of migration, with a log ratio of 4.514, followed by MMP3, MMP1, and IL1β." (PMID 39990676, 2025). "The persistent production of pro-inflammatory cytokines (IL-1β, IL-6, TNF-α) and MMPs (especially MMP-9) alters the extracellular matrix, promotes EMT, and supports tumor invasion and metastasis." (PMID 41322070, 2025). "IL-1β, another proinflammatory cytokine belonging to the IL-1 family, promotes CCL2 expression in macrophages and tumor cells within the TME." (PMID 41341593, 2025). "Mechanistic studies involved the levels of cellular ROS, IL-1β, IL-18 and the expression of caspase-1/3/7/9-GSDMD/E in both cell and tumor tissues were determined by ELISA, immunohistochemistry, Western blot and qRT-PCR." (PMID 40604924, 2025). "The deficiency of STAB1 induced the elevation of inflammatory cytokines (IL1β, IL2, IL12p70, TNFα) and chemokines (CCL3, CCL4, CCL5) in tumor-bearing mice." (PMID 41007347, 2025). "IL-1β regulates tumor therapeutic responses and immune activation, while the LIF-mediated secretory pathway contributes to drug resistance in tumor cells." (PMID 39893499, 2025). "We found that, compared to normal tissues, BAX, CHMP2A, CHMPB, IL1A, IL1B, and VPS24 were more strongly expressed in the cytoplasm and nucleus of tumor tissues." (PMID 39744500, 2025). "As a result, IL-1β upregulates ESE3 expression in PSCs through NF-κB activation, and ESE3 is essential for PSC activation by tumor-derived IL-1β." (PMID 40948749, 2025). "We observed a significant increase in IL‐1β expression and cell death in both MSI and MSS tumor lesions overexpressing YY2 and treated with anti‐PD‐L1 antibody." (PMID 39903759, 2025).